PGAM1 (phosphoglycerate mutase 1)
Description:
Catalyzes the interconversion of 2-phosphoglycerate and 3-phosphoglycerate, a crucial step in glycolysis, by using 2,3-bisphosphoglycerate. Also catalyzes the interconversion of (2R)-2,3-bisphosphoglycerate and (2R)-3-phospho-glyceroyl phosphate.
Synonyms: PGAM-B; PGAMA; HEL-S-35
Tractability: Small molecule: a structure with a bound ligand is known; a high-quality ligand is known; it has a binding pocket of medium quality. Antibody: its Gene Ontology location is reachable by antibodies, with high confidence. PROTAC: ubiquitination databases record sites on it; its protein half-life has been measured; a small molecule that binds it is known.
Target class: Enzyme
Gene: Protein-coding gene on chromosome 10 (97,426,124 to 97,433,444, forward strand). Ensembl gene ENSG00000171314.
Subcellular location (Human Protein Atlas): Nucleoplasm; Mid piece
Pathways (Reactome):
Metabolism: Gluconeogenesis; Glycolysis
Immune System: Neutrophil degranulation
Gene Ontology:
Molecular function: bisphosphoglycerate mutase activity; phosphoglycerate mutase activity; protein binding; protein kinase binding; catalytic activity; intramolecular phosphotransferase activity
Biological process: canonical glycolysis; gluconeogenesis; glycolytic process
Cellular component: cytoplasm; cytosol; extracellular exosome; membrane; extracellular region; ficolin-1-rich granule lumen; secretory granule lumen
Genetic constraint (gnomAD): Loss-of-function variants: 20 observed, 21.64 expected, observed/expected ratio (o/e) 0.92, 90% interval 0.65 to 1.34. The upper end of that interval is the gene's LOEUF score, 1.34, which puts it in group 5 of 6, group 1 being the genes least tolerant of losing a copy. Missense variants: 232 observed, 310.99 expected, observed/expected ratio (o/e) 0.75, 90% interval 0.67 to 0.83. Synonymous variants: 103 observed, 118.74 expected, observed/expected ratio (o/e) 0.87, 90% interval 0.74 to 1.02.
Homologues: Orthologues: chimpanzee PGAM1 (100% identical), macaque PGAM1 (100% identical), macaque PGAM4 (100% identical), dog PGAM1 (99% identical), mouse Pgam1 (99% identical), rat Pgam1 (99% identical), zebrafish pgam1b (91% identical), zebrafish pgam1a (90% identical), tropical clawed frog pgam1 (88% identical), Drosophila melanogaster Pglym78 (68% identical), Drosophila melanogaster Pglym87 (63% identical). Paralogues in human: PGAM4 (96% identical), PGAM2 (81% identical), BPGM (54% identical).
Diseases named in the same sentence as PGAM1 in open-access papers:
PGAM1 is named in the same sentence as 87 diseases in open-access papers, as found by Europe PMC text mining. Sharing a sentence is not in itself a finding about the gene and the disease. The quoted sentences say what the papers report.
breast cancer (34 papers, 2010 to 2025). A primary or metastatic malignant neoplasm involving the breast. "Consistent with the expression of PGAM1 mRNA in EVs associated with breast cancer, there is an upregulated expression of PGAM1 in breast cancer." (PMID 40214422, 2025). "Phosphoglycerate mutase 1 (PGAM1) is a key metabolic enzyme in the glycolysis pathway whose overexpression is associated with breast cancer." (PMID 37719007, 2023). "NEAT1_1 accelerates glycolytic activity in breast cancer through substrate channeling of PGK1, PGAM1, and ENO1, bringing them into close association in the cytoplasm." (PMID 40804479, 2025). "Cell experiments showed that the activity, proliferation, invasion and healing ability of breast cancer cell lines were significantly decreased after knockdown of the key gene PGAM1 in the model." (PMID 37338518, 2023). "Our study provides a new idea for prognostic stratification of breast cancer and provides a novel marker: PGAM1." (PMID 37338518, 2023). "A recent study recognised the assembly of penultimate enzyme complexes, including PGAM1, in breast cancer cells." (PMID 38093528, 2023). "PAGM1 was highly expressed in breast cancer, and K-M survival analysis suggested that patients with high expression of PGAM1 have a poor prognosis (p<0.01)." (PMID 37338518, 2023). "CCK-8 assay showed that the activity of MDA-MB-231 and MDA-MB-468 breast cancer cell lines was significantly decreased after PGAM1 knockdown." (PMID 37338518, 2023). "Here, we report that PGAM1 expression is upregulated and related to poor prognosis in patients with breast cancer (BC)." (PMID 35674458, 2022). "PGAM1 was found in higher abundance in metastatic mammary tumor cells than primary tumor cells, which coincides with its tumor progression function, which is observed in higher amounts." (PMID 33668689, 2021). "Several studies reported that PGAM1 is overexpressed in various cancers, including hepatocellular carcinoma, lung cancer, breast cancer, prostate cancer and renal clear cell carcinoma." (PMID 34221971, 2021). "One study showed that PGAM1 is elevated in breast cancer stem cells, but its role in colon cancer stem cells is not understood." (PMID 34845203, 2021). "Through the interaction with ACTA2, phosphoglycerate mutase 1 (PGAM1) mediates the actin filament assembly and increases cell migration and invasion in breast cancer." (PMID 34439090, 2021). "PGAM1 was over-expressed in different types of cancer such as hepatocellular carcinoma, breast carcinoma and colorectal cancer." (PMID 33053689, 2020). "In an in vitro breast cancer model, PGAM1 directly interacted with α-smooth muscle actin (ACTA2) and modulated actin filament assembly, cell mobility, and migration." (PMID 30691108, 2019). "PGAM1 is overexpressed in breast cancer, and suppression of PGAM1 can inhibit breast cancer cell proliferation." (PMID 23118872, 2012). "Recently, chemistry-based functional proteomics was applied to screen for drug target against breast cancer, and phosphoglycerate mutase 1 (PGAM1) was identified as a novel metabolic enzyme involved in breast carcinogenesis." (PMID 20403181, 2010). "A recent study revealed that PGAM1 was overexpressed in breast cancer, and suppression PGAM1 expression displayed a profound antiproliferative effect, underscoring its important role in carcinogenesis." (PMID 20403181, 2010). "Finally, cell experiments verified the function of the key gene PGAM1 in the model, providing a potential biomarker for breast cancer." (PMID 37338518, 2023). "Knockdown of phosphoglycerate mutase 1 (PGAM1) could reconstruct the expression of ASS1 in breast cancer (BC) cells, resulting in a decrease in tumor growth and exerting antitumor effects via cAMP/AMPK/CEBPB axis." (PMID 35674458, 2022). "Therefore, the level of PGAM1 seems to predict the prognosis of various tumors, such as lung cancer, breast cancer, lymphoma and so on." (PMID 36387908, 2022).
breast cancer (continued). "PGAM1 was found with decreased expression in primary and metastatic mammary tumors cells that were treated with rapamycin, which may show a possible rapamycin suppression on this protein." (PMID 33668689, 2021). "Knocking down PGAM1 decreased the metastatic potential of breast cancer cells in vivo." (PMID 30691108, 2019). "Also in our lab, we have demonstrated diagnostic potential of TPI, MNSOD, PGAM1, MUC1 & CMYC autoantibodies in canine mammary tumours by ELISA." (PMID 30361548, 2018). "Several investigations demonstrated that PGAM1 was overexpressed in a variety of human cancers, including breast carcinoma; colorectal cancer; lung cancer; prostate cancer; oral squamous cell carcinoma; esophageal squamous cell carcinomas; and also associated with certain virus infection." (PMID 20403181, 2010). "Furthermore, a recent study showed that a PGAM1 peptide inhibitor induced cancer cell growth arrest in breast carcinoma." (PMID 20403181, 2010). "Elevated levels of NEAT1 in breast cancer enhance glycolysis by scaffolding key glycolytic enzymes, including PGK1, PGAM1, and ENO1, concurrently within the same cellular context, thereby promoting breast cancer progression and metabolism." (PMID 40711448, 2025). "Supporting this finding, a recent study demonstrated that the depletion of PGAM1 by siRNA inhibited the proliferation, invasion, migration, and EMT of MDA-MB-231 and MCF-7 breast cancer cells." (PMID 40214422, 2025). "Clonal formation experiments showed that after PGAM1 knockdown, the proliferation ability of MDA-MB-231 and MDA-MB-468 breast cancer cell lines was significantly reduced." (PMID 37338518, 2023). "Suppression of an important glycolytic enzyme, phosphoglycerate mutase 1 (PGAM1), sensitized BRCA1/2-proficient breast cancer to PARP inhibitors by impairing homologous recombination repair." (PMID 36793373, 2023). "Correlation analysis between PGAM1, ASS1, and clinicopathologic features of the patients with breast cancer." (PMID 35674458, 2022). "Other genes were associated with cell adhesion and migration of breast cancer cell [DUOXA1 and PGAM1], prognosis of breast cancer [PGK1 and KLK10], or clinical outcome in breast cancer [RBM3 and AQP5]." (PMID 34497807, 2021). "The multiplex assay, comprising a panel of candidate autoantigens (TPI, PGAM1, MNSOD, CMYC & MUC1) was used for screening circulating autoantibodies in 125 dog sera samples, including 75 mammary tumour sera and 50 healthy dog sera." (PMID 30361548, 2018). "Overall, these findings indicate that PGAM1 is a cell survival factor via immune cell suppression and a cell progression factor via the promotion of proliferation, invasion, migration, and EMT in breast cancer." (PMID 40214422, 2025). "Similar to NEAT1 in breast cancer, the c-Myc-responsive lncRNA glycoLINC (gLINC) promotes glycolysis by acting as a scaffold for glycolytic enzymes, including PGK1, ENO1, PKM2, and LDHA, with indirect binding to PGAM1." (PMID 40804479, 2025). "Moreover, the anti-cancer effect of some herbal compounds such as Eupatilin on breast cancer has not been studied, or new targeting pathways for cancer prevention have been introduced including Malic enzyme 2 and Phosphoglycerate mutase 1 that are noteworthy." (PMID 32952942, 2020).
hepatocellular carcinoma (19 papers, 2010 to 2025). A malignant tumor that arises from hepatocytes. "PGAM1 is also markedly upregulated in hepatocellular carcinoma (HCC) and has potential as a diagnostic biomarker and potential therapeutic target for HCC." (PMID 23118872, 2012). "Our studies suggested that PGAM1 plays an important role in hepatocarcinogenesis, and should be a potential diagnostic biomarker, as well as an attractive therapeutic target for hepatocellular carcinoma." (PMID 20403181, 2010). "The data presented in this study suggested that PGAM1 could be developed as a useful diagnostic biomarker, as well as a potential therapeutic target for hepatocellular carcinoma." (PMID 20403181, 2010). "The specific mechanism is that circDDX21 promotes glycolysis through upregulating PGAM1 expression, thereby facilitating the in-vivo growth of hepatocellular carcinoma cells." (PMID 41169378, 2025). "Accumulating studies have revealed that PGAM1 is frequently overexpressed in various human cancers and correlates with poor prognosis and increased metastasis, including colon, breast, lung, and hepatocellular carcinoma 11-17." (PMID 38434965, 2024). "In this study, we show that consistent with the enhancing effect of circDDX21 on PGAM1 expression, circDDX21 is able to promote both in vitro hepatocellular carcinoma cell proliferation and in vivo xenograft tumor growth via PGAM1." (PMID 38773094, 2024). "PGAM1 is frequently upregulated in various human cancers, including breast cancer, lung cancer, and hepatocellular carcinoma." (PMID 38773094, 2024). "While regulation of the miR-299-3p/phosphoglycerate mutase 1 (PGAM1) axis related to the constrained EMT was elicited by matrine in hepatocellular carcinoma cells." (PMID 37446730, 2023). "In the upregulated gene pool, Pgam1 promotes cancer cell migration, while Ppia has been shown to be correlated with poor prognosis in patients with hepatocellular carcinoma." (PMID 34421639, 2021). "The results showed that sja-miR-61 significantly down-regulated the levels of PGAM1 in hepatoma cells compared to the NC or Mock controls." (PMID 34221971, 2021). "This schistosome miRNA suppressed tumor cell migration in vitro and growth of hepatoma in vivo through anti-angiogenesis by targeting PGAM1 gene." (PMID 34221971, 2021). "PGAM1 has been identified as a potential therapeutic target in hepatocellular carcinoma, however, its implication in cancer cell proliferation remains poorly understood and little is known on its regulation." (PMID 25932951, 2015). "Hopefully, shRNA-mediated suppression of PGAM1 expression, combined with conventional surgical resection and chemotherapy strategies, will open a new avenue for clinical treatment of hepatocellular carcinoma." (PMID 20403181, 2010). "Furthermore, circDDX21 expression was positively correlated with PGAM1 expression in all the examined hepatocellular carcinoma tissue samples (n = 51), indicating the biological importance of the circDDX21-PGAM1 axis in hepatocellular carcinogenesis." (PMID 38773094, 2024). "The expression of circDDX21 and PGAM1 are also positively correlated in hepatocellular carcinoma." (PMID 38773094, 2024). "Additionally, in clinical hepatocellular carcinoma tissues, there is a positive correlation between circDDX21 and PGAM1 expression." (PMID 38773094, 2024). "For instance, PGAM1, a key enzyme of glycolysis, accelerates carcinogenesis once hyper-activated; aspirin is capable of attenuating PGAM1 activity by removing its K99 succinylation in hepatoma cells that ultimately leads to halted tumor progression." (PMID 36605449, 2022). "Histone acetyltransferase 1 (HAT1) is another recently identified succinyl-transferase, which promotes glycolysis and thus tumorigenesis in, e.g., human hepatoma cells and pancreatic cancer cells by enhancing the enzymic activity of PGAM1 via K99 succinylation." (PMID 36605449, 2022).
hepatocellular carcinoma (continued). "Importantly, restoration of PGAM1 level led to abolishment of the sja-miR-61-mediated inhibition of the migration of the hepatoma cell in both cell lines." (PMID 34221971, 2021). "PGAM1 immunoreactivity in normal liver tissues and hepatocellular carcinoma tissues." (PMID 20403181, 2010). "In a model of hepatocellular carcinoma (HCC), Pgam1 is reported to be a novel immunometabolic target and inhibition of Pgam1 promotes HCC ferroptosis through inducing CD8+ T-cell infiltration 45, suggesting a linkage between Pgam1 and inflammation." (PMID 39659576, 2024). "Therefore, circDDX21 exerts its tumor-promoting effect by regulating the ubiquitination of PABPC1 to elevate the level of PGAM1 protein in hepatocellular carcinoma (HCC) cells." (PMID 41169378, 2025). "By suppressing phosphoglycerate mutase 1 (PGAM1), the downregulation of lipocalin-2 (LCN2) promotes ferroptosis in hepatocellular carcinoma cells and facilitates the recruitment of CD8+ T cells." (PMID 39420203, 2024). "Phosphoglycerate mutase 1 (PGAM1) inhibition can promote ferroptosis and bolster anti‐tumor immunity in hepatocellular carcinoma (HCC)." (PMID 37705495, 2023).
lung cancer (14 papers, 2010 to 2025). A malignant neoplasm involving the lung. "Increased levels of PGAM1 protein in tissues of patients with lung cancer are associated with poor clinical prognosis." (PMID 34435138, 2021). "PGAM1 is highly expressed in nonsmall cell lung cancer tissues and is associated with poor prognosis." (PMID 32167655, 2020). "To further assess the functional interplay between SEC61G and UBE3C, we examined the effects of SEC61G expression changes on PGAM1 levels in lung cancer cell lines." (PMID 39990664, 2025). "In summary, SEC61G physically interacts with PGAM1 in lung cancer cells, and both proteins exhibit cytoplasmic co-localization, supporting their functional association." (PMID 39990664, 2025). "EGCG effectively inhibited PGAM1 in the form of a liposome that had a greater ability to penetrate through the cell membrane in H1299 lung cancer cells." (PMID 35628385, 2022). "The results suggest that the expression of PGAM1 is mTOR dependent in rodent cells and human lung cancer." (PMID 29362480, 2018). "In an experiment using mouse lung cancer xenografts, the anti-tumor activity of PGMI-004A was confirmed by the inhibition of tumor growth and the inhibition of PGAM1 activity in resected tumors." (PMID 35628385, 2022). "To investigate whether SEC61G regulates PGAM1 at the protein level, we assessed the stability of PGAM1 in SEC61G-overexpressing lung cancer cells using the protein synthesis inhibitor cycloheximide (CHX)." (PMID 39990664, 2025).
glioma (8 papers, 2014 to 2024). A benign or malignant brain and spinal cord tumor that arises from glial cells (astrocytes, oligodendrocytes, ependymal cells). "For instance, PGAM1 has been implicated in the activation of DNA damage repair pathways, as shown in gliomas where it interacts with Wip1, inhibiting its translocation into the nucleus and consequently attenuating the ATM signaling pathway." (PMID 38434965, 2024). "Accumulating evidence has demonstrated that PGAM1 is upregulated in some types of tumors, including gliomas, bladder cancer, non‐small cell lung cancer (NSCLC), and renal clear cell carcinoma." (PMID 35674458, 2022). "As a result of its dynamic role in metabolic coordination, PGAM1 is overexpressed in several cancer types, including gliomas, oral carcinomas and pancreatic cancers." (PMID 33834022, 2021). "Complementary studies in gliomas cells demonstrated that depletion of PGAM1 also led to defective DNA damage signaling, including ATM autophosphorylation and phosphorylation of its downstream substrates." (PMID 33834022, 2021). "This led to disrupted DSB repair and subsequent sensitivity to IR, suggesting that PGAM1 may be a potential therapeutic target in gliomas." (PMID 33834022, 2021). "PGAM1 has been reported to be overexpressed in high grade glioma." (PMID 25932951, 2015). "We selected seven glycolytic genes (HK2, PFKP, ALDOA, PGAM1, ENO1, ENO2 and PDK1) and confirmed their strong up-regulation under hypoxia by QPCR in seven GBM cell lines (five patient derived glioma stem-like cells and two adherent GBM cell lines)." (PMID 25932951, 2015). "Interestingly, WIP1 function can be regulated by phosphoglycerate mutase 1 (PGAM1), a glycolytic enzyme that is overexpressed in cancer tissues and that is able to block WIP1 cytoprotective function upon chemo- and radiotherapy in glioma." (PMID 36340043, 2022). "This is highly similar to the negative correlation between PGAM1 and OS in NSCLC, OSCC, glioma and BRCA." (PMID 38434965, 2024).
prostate carcinoma (8 papers, 2018 to 2026). A carcinoma that arises from epithelial cells of the prostate gland. "Nevertheless, the underlying mechanism of exosomal PGAM1 in prostate cancer (PCa) metastasis remains unclear." (PMID 37542027, 2023). "PGAM1 is often upregulated in various cancers, including breast, lung, and prostate cancers, contributing to tumor growth and progression by coordinating glycolysis and anabolic processes which makes it an appealing target for drug development." (PMID 42116375, 2026). "PGAM1 is highly expressed in various tumors, such as oral squamous cell carcinoma, prostate cancer, non-small cell lung cancer, renal clear cell carcinoma, pancreatic ductal carcinoma, and colorectal cancer, and is associated with tumor invasion, migration, and proliferation." (PMID 35925486, 2022).